CXCR4 (C-X-C motif chemokine receptor 4)
Diseases named in the same sentence as CXCR4 in open-access papers (continued):
Sharing a sentence is not in itself a finding about the gene and the disease.
cyst (2 papers, 2016 to 2020). A sac-like closed membranous structure that may be empty or contain fluid or amorphous material. "Similarly, our study suggests that targeting epithelial CXCR4+ cells may prevent honeycomb cyst formation in IPF and other fibrotic ILDs that share the UIP pattern." (PMID 32843095, 2020).
deafness (2 papers, 2018 to 2022). An inherited or acquired condition characterized by the complete loss of the ability to hear from one or both ears. "CXCR4 mRNA expression was 3.9-fold higher in patients with slight hearing loss (H1/2), 4.6-fold higher in patients with moderate hearing impairment (H3/4), and 5-fold higher in patients with severe hearing loss or deafness (H5/6) compared to the control group." (PMID 29515781, 2018).
deep vein thrombosis (2 papers, 2014 to 2024). "In a mouse thrombosis model, when CXCR4 was antagonized with AMD3100, the accumulation of BSDL was inhibited and thrombus size was reduced." (PMID 24505417, 2014). "Several recent studies have associated the inhibition of the CXCR4/CXCL12 axis with a reduction in both arterial and venous thrombus formation, with increased circulating levels of CXCL12 and Pim-1 observed in deep vein thrombosis." (PMID 39062849, 2024). "Many systemic inflammatory diseases such as rheumatoid arthritis, systemic lupus erythematous, and familial Mediterranean fever have upregulated CXCR4 and/or increased circulating plasma levels of CXCL12, and these conditions also carry a predisposition to thrombosis." (PMID 39062849, 2024).
demyelination (2 papers, 2012 to 2020). "Accordingly, reduced numbers of CXCR4 + OPCs were observed within the CC of TNFR2-deficient mice during CPZ-induced demyelination." (PMID 22933014, 2012).
Duchenne muscular dystrophy (2 papers, 2012 to 2020). Duchenne muscular dystrophy (DMD) is a neuromuscular disease characterized by rapidly progressive muscle weakness and wasting due to degeneration of skeletal, smooth and cardiac muscle. "Additionally, recent reports described the use of gold nanoparticles for the delivery of clustered regularly interspaced short palindromic repeats CRISPR/Cas9 for the editing of the CXCR4 gene or the dystrophin gene, associated with Duchenne muscular dystrophy (DMD) disease." (PMID 32560390, 2020). "Therefore, we sought to translate these results to a clinically relevant canine-to-canine allogeneic transplant model for Duchenne muscular dystrophy (DMD) and determine if CXCR4 is important for donor cell engraftment." (PMID 22340947, 2012).
ductal carcinoma (2 papers, 2018). "CXCR4 staining in ductal carcinoma was mainly present in the cytoplasm and cell surface, particularly around the ducts, whilst in lobular carcinoma staining was mostly cytoplasmic but was also present in the nucleus of most infiltrating cells." (PMID 30441765, 2018). "ACKR3 staining followed the same pattern as CXCR4—in ductal carcinoma ACKR3 was exclusively present in the cytoplasm and although it was also mostly cytoplasmic in lobular carcinoma, infiltrating cells also presented nuclei staining." (PMID 30441765, 2018).
ductal carcinoma in situ (2 papers, 2010 to 2011). "Notably, CXCR4 protein was observed by Schmid and colleagues in 13 of 14 cases of ductal carcinoma in situ of the breast, as well as in 13 of 14 areas of atypical ductal hyperplasia of the breast." (PMID 21179547, 2010).
embryonal carcinoma (2 papers, 2015 to 2023). A non-seminomatous malignant germ cell tumor characterized by the presence of large germ cells with abundant cytoplasm resembling epithelial cells, geographic necrosis, high mitotic activity, and pseudoglandular and pseudopapillary structures formation. "Although, in CXCR4- / CXCR7--embryonal carcinoma cells, CXCR7-expression was re-induced upon inhibition of ERK1 / 2-signaling." (PMID 37996954, 2023). "DMSO-treated P19CL6 embryonal carcinoma cells transiently adopt a mesendodermal-like state, as judged by robust coexpression of Lhx1, Eomes, T, Foxa2, and Cxcr4." (PMID 26494787, 2015).
encephalitis (2 papers, 2025 to 2026). An acute inflammatory process affecting the brain parenchyma. "Our study also did not assess potential recruitment of non-T cell populations expressing CXCR4 and CXCR6 during MuPyV encephalitis." (PMID 40581668, 2025).
endometritis (2 papers, 2016 to 2020). An acute or chronic, usually bacterial infectious process affecting the endometrium. "The expression patterns of only 28 genes in subclinical endometritis have been substantially altered, of which 26 genes including PTHLH, INHBA, DAPL1, MAOB, CXCR4, and TGIF1 were identified in both subclinical and clinical endometritis." (PMID 33426032, 2020). "There are 92 genes, including PTHLH, INHBA, DAPL1, and SERPINA1, which were significantly highly regulated and 111 genes which had significantly poorly regulated expression levels, including MAOB, CXCR4, HSD11B, and BOLA, as recorded in clinical endometritis." (PMID 33426032, 2020).
ependymoma (2 papers, 2014 to 2020). A WHO grade II, slow growing tumor of children and young adults, usually located intraventricularly. "The ependymoma cells were found positive to Nanog (13%), CD133 (47.5%), CD44 (65.5%), and CXCR4 (89.7%) when compared to an isotype control antibody." (PMID 25144312, 2014).
esophageal tumor (2 papers, 2021). "In the majority of studies, overexpression of CXCR4 had been investigated in esophageal tumors or its metastases." (PMID 33579381, 2021). "CXCR4 is highly expressed in esophageal tumor stem cells, and the expression of CXCR4 in CSCs increases the malignant potential of ESCC and is associated with ESCC recurrence and metastasis." (PMID 33710803, 2021). "In case of overexpression of CXCR4 in esophageal tumours or their metastases, an additional Pentixafor PET/CT could detect further localisations not visible in FDG PET/CT." (PMID 33579381, 2021).
follicular carcinoma (2 papers, 2020 to 2021). "The biological roles of CXCL12 also were founded in THCA, in which CXCR4/CXCR7/CXCL12 axis offer new valuable insight into the oncogenesis of metastatic follicular thyroid carcinoma." (PMID 32714651, 2020).
gastric ulcer (2 papers, 2015 to 2022). An ulcerated lesion in the mucosal surface of the stomach. "These activated TP+ platelets released VEGF‐A and SDF‐1 and induced mobilization of VEGFR1+CXCR4+ cells from BM and their accumulation in ischaemic muscle and in gastric ulcer areas." (PMID 34655121, 2022). "SDF-1/CXCR4-induced gastric ulcer healing depends on VEGFR1-TK signaling." (PMID 26133989, 2015). "We have already reported that BM-derived CXCR4+VEGFR1+ induce gastric ulcer healing and tumor metastasis, but it remains unclear whether VEGFR1 signaling and the recruitment of BM cells are involved in the recovery of ischemic tissues remains to be elucidated." (PMID 26133989, 2015).
gingivitis (2 papers, 2022 to 2023). A disorder involving inflammation of the gums; may affect surrounding and supporting structures of the teeth. "IL1B, CXCR4 mRNA were up-regulated in gingivitis samples compared with normal tissues (P < .05)." (PMID 37986309, 2023).
glaucoma (2 papers, 2015 to 2020). Increased pressure in the eyeball due to obstruction of the outflow of aqueous humor. "In conclusion, reduction in IL-6 would help in reducing the effects of glaucoma as with the other inflammatory cytokines of CXCR4, IL-17, IL-1β, and TNF-α which are known to be increased in PC-12-glaucoma model cells without betalain treatment." (PMID 32666339, 2020). "However, little is known regarding the involvement of CXCR4 in the mechanisms of action of TMP related to glaucoma treatment." (PMID 26275042, 2015). "Using RT-PCR and western blot assays, we determined that glaucoma-related cytokines and dexamethasone (DEX) also significantly up-regulated CXCR4 expression in primary human trabecular meshwork (PHTM) cells." (PMID 26275042, 2015). "CXCR4 expression was examined by quantitative real-time PCR in trabecular and iris specimens from 54 primary open-angle glaucoma (POAG) patients who required surgery and 19 non-glaucomatous donors." (PMID 26275042, 2015). "Thus, we speculated that CXCR4 is involved in the pathogenesis of glaucoma rather than a result of inflammatory infiltration." (PMID 26275042, 2015).
glomerular diseases (2 papers, 2014 to 2022). "CXCR4 upregulation has previously been described as a feature of a hypoxia-related glomerulopathy in patients with hypertensive nephrosclerosis." (PMID 24637920, 2014). "In view of that CXCR4 and β-catenin are upregulated in the glomeruli of several CKD models, future studies using other models of glomerular diseases or intervention strategies are warranted." (PMID 34976212, 2022).
Hearing impairment (2 papers, 2018 to 2019). A decreased magnitude of the sensory perception of sound. "In the future, routine assessment of CXCR4 expression might be an option for evaluating the risk of individual patients for hearing impairment." (PMID 29515781, 2018). "Cytokines produced by VS, especially CXCR4 expression, have been related to hearing impairment." (PMID 31620068, 2019).
helminth infection (2 papers, 2012 to 2022). "Notably, ILC2 and Th2 cells showed significant baseline CXCR4 expression, enhanced following helminth infection, reaching up to 80% of ILC2s." (PMID 35288645, 2022). "The L. sigmodontis filarial infection is a Th2-based helminthiasis and the CXCL12/CXCR4 axis has been reported to have a role in numerous Th2-based inflammatory diseases." (PMID 22511975, 2012). "Both ILC2s and macrophages expressed the MIF receptor CXCR4, indicating that MIF may act as an essential co-factor on both cell types to activate responses to IL-25 in helminth infection." (PMID 35288645, 2022).
hemangiosarcoma (2 papers, 2015 to 2016). "Mir-150 also plays a role in regulation of CXCR4, with decreased expression of mir-150 (as was seen in the hemangiosarcoma samples) leading to increased expression of CXCR4 protein." (PMID 27912752, 2016). "In vitro, CXCL12 promoted cell migration and invasion of hemangiosarcoma cells, and these responses were also sensitive to the CXCR4 antagonist, AMD3100." (PMID 29061946, 2015). "Considering the proposed bone marrow origin of hemangiosarcoma, hemangiosarcoma cells expressing CXCR4 on their cell surface may represent a progenitor population that is maintained by CXCL12-abundant reticular cells in this niche." (PMID 29061946, 2015). "In hemangiosarcoma, the heterogeneous expression of CXCR4 and CXCL12 was reported in hemangiosarcoma cell lines and whole tumor tissues by transcriptome analysis." (PMID 29061946, 2015). "The potential also exists that CXCR4 and CXCL12 expression may be regulated through beta adrenergic signaling, and beta blockade may prevent the expansion of hemangiosarcoma progenitor cells from the bone marrow or the migration of these cells to CXCL12-rich sites, reducing metastatic spread." (PMID 29061946, 2015).
hyperlipidemia (2 papers, 2022). "Similarly, SMC accumulation in murine lesions was reduced in a hyperlipidemia-model with SMC-specific CXCR4 deletion and in an injury-model with endothelial-specific CXCR4 deletion." (PMID 35055054, 2022).
infectious mononucleosis (2 papers, 2013 to 2014). A condition characterized by an increase in mononuclear white blood cells and swollen lymph nodes, which is usually caused by infection with the Epstein-Barr virus. "Neither the CXCR4 nor the CCR10 markers conform with the phenotypic relationship with LCL cells and with EBV positive B cells localized at the periphery of tonsil in infectious mononucleosis." (PMID 25162594, 2014).
insulinoma (2 papers, 2022 to 2024). "We investigated the relationship between SAP‐silenced CAFs and activation of the CXCL12/CXCR4/p38/ERK pathway in insulinoma." (PMID 38766687, 2024). "Furthermore, we demonstrate that SAP deletion‐induced upregulation of CXCL12/CXCR4 promotes insulinoma growth and metastasis by activating the p38/ERK signalling pathway." (PMID 38766687, 2024). "Here, we found that SAP deletion promoted CXCL12 secretion by CAFs, which activated the CXCR4/p38/ERK signalling pathway, thereby promoting insulinoma growth, invasion and metastasis in Rip1‐Tag2 mice." (PMID 38766687, 2024). "We first investigated the expression of CXCR4, the receptor for CXCL12, and found that CXCR4 expression was upregulated in both NIT‐1 cells and RIN‐m5F insulinoma cells." (PMID 38766687, 2024).
intracerebral hemorrhage (2 papers, 2023). A cerebrovascular disorder characterized by bleeding into one or both cerebral hemispheres including the basal ganglia and the cerebral cortex. "CXCL12 signals through CXCR4 and plays a critical role in angiogenesis in experimental intracerebral hemorrhage." (PMID 37817190, 2023). "In this study, we investigated the role of SDF‐1/CXCR4 in neural functional injury and neuroprotection after intracerebral hemorrhage (ICH)." (PMID 37614198, 2023).
joint diseases (2 papers, 2020 to 2022). "The evidence reveals that the SDF‐1/CXCR4 axis is closely related to various types of joint diseases." (PMID 32449535, 2020).
kidney tumor (2 papers, 2018 to 2023). "In particular, data regarding the subcellular distribution of CXCR4 in RCC and RCC metastasis as well as CXCR4 expression in renal tumors of variant histology are limited." (PMID 36982302, 2023). "CXCR4 expression differs significantly within benign lesions and renal neoplasms." (PMID 36982302, 2023).
left ventricular hypertrophy (2 papers, 2015 to 2022). Enlargement of the LEFT VENTRICLE of the heart. "The data collected throughout this study suggest the deletion of CXCR4 in endothelial cells is linked to the development of aortic valve stenosis and left ventricular hypertrophy." (PMID 36148060, 2022). "We demonstrated that mice with deletion of CXCR4 in endothelial cells develop hemodynamically significant aortic valve stenosis and left ventricular hypertrophy." (PMID 36148060, 2022).
lentivirus infection (2 papers, 2011 to 2016). Virus diseases caused by the Lentivirus genus. "We measured the CXCR4 expression using flow cytometry 6 days after lentivirus infection." (PMID 27057542, 2016).
leprosy (2 papers, 2021 to 2024). Leprosy is a chronic infectious disease affecting primarily the skin and peripheral nervous system. "Cxcr4 expression is reduced in the lymphocytes of leprosy patients but increased in M. tuberculosis-infected macrophages." (PMID 33826679, 2021). "CXCR4 may drive the recruitment of lymphocytes to tissue lesions of leprosy patients." (PMID 38739634, 2024).
liver cirrhosis (2 papers, 2022 to 2025). "In the context of liver cirrhosis, the chemokine receptor CXCR4 and its ligands, particularly CXCL12, are crucial." (PMID 41223189, 2025). "Among them, CCR7, CXCL12, CXCR4, and CXCL8 were observed to have significantly elevated expression in liver cirrhosis samples." (PMID 41223189, 2025).
Lung Adenosquamous Carcinoma (2 papers, 2020 to 2022). "Indeed it was found that CXCR4 is highly expressed in many specimens of lung adenosquamous carcinoma." (PMID 35064116, 2022).
malignant peripheral nerve sheath tumor (2 papers, 2017). Malignant peripheral nerve sheath tumor (MPNST) is a rare and often aggressive soft tissue sarcoma occurring in a wide range of anatomical sites. "Malignant peripheral nerve sheath tumors (MPNSTs) are aggressive, Schwann cell-derived neoplasms of the peripheral nervous system that have recently been shown to possess an autocrine CXCL12/CXCR4 signaling loop that promotes tumor cell proliferation and survival." (PMID 28055968, 2017).
malignant pleural mesothelioma (2 papers, 2017 to 2024). A malignant neoplasm that arises from mesothelial cells in the pleura and shows a diffuse growth pattern. "This study investigated the feasibility of CXCR4-directed imaging with positron emission tomography/computed tomography (PET/CT) using [68Ga]Pentixafor in malignant pleural mesothelioma." (PMID 29228566, 2017).
metastatic colorectal cancer (2 papers, 2012 to 2024). "Our study demonstrates that chloroquine and hydroxychloroquine are antagonists to CXCR4 and thus provides a molecular basis for using chloroquine in patients with metastatic colorectal cancer." (PMID 22319600, 2012).
monocytopenia (2 papers, 2015 to 2019). "Indeed, WHIM (warts, hypogammaglobulinemia, infections, and myelokathexis) syndrome, an autosomal dominant disorder often accompanied by monocytopenia, is caused by a single amino acid mutation in CXCR4, which blocks its endocytosis and therefore increases CXCR4 activity }." (PMID 26029924, 2015).
oral lichen planus (2 papers, 2020 to 2025). Oral lichen planus is a chronic inflammatory oral condition of unknown aetiology characterized by T-cell-mediated chronic immune response and abnormal epithelial keratinization cycle. "We further validated our predictions and found that CXCR4 was upregulated in all oral lichen planus tissue samples." (PMID 32214134, 2020). "Notably, fibroblasts were the source of CXCL12 and interacted with the receptors of CXCR4 on T cells and NK cells, suggesting an important role of fibroblasts in recruiting immune cells in oral lichen planus." (PMID 40574847, 2025).
osteonecrosis (2 papers, 2022 to 2024). A none disease characterized by death of bone tissue due to a lack of blood supply. "A decreased expression of some cytokines in cultured GD macrophages has been described for CCL5/RANTES and CXCR4, while the serum level of CCL5/RANTES is elevated in GD patients with osteonecrosis." (PMID 38667330, 2024).
pancreatic NEC (2 papers, 2024). "The proportion of CXCR4 overexpression was the highest in pancreatic NEC patients (66.7%), followed by colorectal (57.1%), gallbladder (50.0%), esophagus (25.0%) and stomach (15.0%)." (PMID 38524630, 2024). "E, F A 68-year-old patient with initial diagnosis of a pancreatic NEC and local lymph node metastases only seen on CXCR4 PET." (PMID 38332341, 2024).
peripheral T cell lymphoma (2 papers, 2020 to 2021). "Weng AP and the colleagues reported that only 11.5% (3/26) of the cases with peripheral T cell lymphoma exhibited positive immunohistochemical staining for CXCR4." (PMID 32757068, 2020).
pneumonia (2 papers, 2020 to 2025). An acute, acute and chronic, or chronic inflammation focally or diffusely affecting the lung parenchyma, caused by an infection in one or both of the lungs (by bacteria, viruses, fungi, or mycoplasma.). "In conclusion, our data indicate that CXCR4 antagonism reduces pneumonia severity in a pharmacological mouse model of CXCR2 LOF, and this effect is likely associated with the normalization of neutrophil numbers in infected tissues." (PMID 41451234, 2025). "The ability of the CXCR4 antagonist to reduce pneumonia in our CXCR2 LOF mice is likely related to its ability to mobilize neutrophils and facilitate their emigration into infected tissues rather than directly influencing neutrophil effector functions." (PMID 41451234, 2025). "Furthermore, CXCR4 antagonism ameliorated the severity of pneumonia and facilitated the emigration of neutrophils into infected tissues in the CXCR2 LOF mice." (PMID 41451234, 2025). "Furthermore, our results demonstrate that CXCR4 antagonism reduces the severity of pneumonia in the CXCR2 LOF mice and facilitates the emigration of neutrophils into bacterially infected lung tissue." (PMID 41451234, 2025). "Additionally, CXCR4 antagonism mitigated the severity of pneumonia in CXCR2 LOF mice and facilitated neutrophil emigration into bacterially infected tissues." (PMID 41451234, 2025).